BCL2 (BCL2 apoptosis regulator)
Diseases named in the same sentence as BCL2 in open-access papers (continued):
Sharing a sentence is not in itself a finding about the gene and the disease.
tumor (continued). "The western blotting assays of tumor tissue lysates showed that TSN inhibited the PI3K/Akt/mTOR signaling pathway and the expression of MMP-2, cyclin D1, and Bcl-2 proteins." (PMID 34530814, 2021). "We profiled the apoptosis-related proteins (Bcl-2, Bcl-xL, Survivin, PARP, and procaspase 3) in tumor tissues of the xenograft MM mouse model." (PMID 34771643, 2021). "We observed a marked decrease in Bcl-2, Bcl-xL, Survivin, full-length PARP, and procaspase-3, thus indicating that Tris DBA can interfere with tumor development by inducing apoptosis in tumor cells." (PMID 34771643, 2021). "Nude mice xenografts, established using HCC cells, were treated with 25 mg/kgd Icariside II for 30 days and exhibited a remarkable reduction in tumor volume, weight, and the protein levels of MMP2/9 and BCL-2/Bax ratio compared to the DMSO-treated group." (PMID 33981241, 2021). "Difference in methylation levels of Beclin-1, bcl2, LC3 and ULK1 genes in tumor samples compared to normal tissues were analyzed." (PMID 33773561, 2021). "In tumor tissues from galangin treated mice, the ratios of p-JAK2/JAK2 and p-STAT3/STAT3, as well as the protein expressions of Bcl-2, caspase-3 and Ki67 were all reduced remarkably (p < 0.01 or p < 0.001)." (PMID 33981228, 2021). "In PE/CA-PJ49 tumor cells, combined treatment with CisPt + RSV (p < 0.05, *) decreased BCL-2 gene expression compared to the effect induced by RSV applied alone." (PMID 34204834, 2021). "To investigate the role of ICT1 in tumor growth in vivo, we established a xenograft model by stably silencing ICT1 and transfecting BCL-2 into U-2OS cells." (PMID 33585660, 2021). "As previously reported, quercetin and crocetin were able to inhibit MAPK- or PI3K/AKT-mediated BCL-2 expression; promote the expression of caspase-3, caspase-8, caspase-9, and PARP so that tumor cells-cycle was inhibited, and apoptosis of tumor cell initiated." (PMID 34098848, 2021). "Other BCL-XL and BCL-2 dual inhibitors developed subsequently (e.g. AZD4320, BM-1197, S44563, APG-1252) also demonstrated similar long-lasting tumour regression in SCLC, gastric and uveal melanoma xenograft models." (PMID 34581776, 2021). "miR-21 can activate NF-κB, STAT3 and bcl-2 signaling pathways by targeting PDCD4, thus reducing apoptosis in tumor cells." (PMID 34305614, 2021). "First, we investigated the expression of Bcl-2 and XIAP, both of them were recognized as anti-apoptosis markers, which suppressed the tumor apoptosis effect." (PMID 34071132, 2021). "The immunoexpression of IAP-2, Bcl-2, and GLUT1 in the peripheral cells of the solid area of the tumour was commonly observed." (PMID 34987583, 2021). "In MM, however, BH3 profiling has revealed tumor-cell dependency on anti-apoptotic proteins to be highly heterogeneous, with primary MM cells at diagnosis being dependent on MCL-1 or BCL-2, or co-dependent on either BCL-2/MCL-1 or BCL-XL/MCL-1." (PMID 33806619, 2021).
tumor (continued). "ULK1/2 is a known inhibitor of BCL2/adenovirus E1B 19 kDa interacting protein 3 (BNIP3) 27, the atypical BH3-only protein which functions as a tumor suppressor in human cancers 28-30." (PMID 34345207, 2021). "Although there are promising indications for BCL-2 inhibition in solid tumors, BCL-XL is more often found to be upregulated in these tumors and of all tumor types, amplification is most often detected in CRC." (PMID 34117376, 2021). "We further performed western blotting to detect the protein expression of JWA, CDK12, Bcl-2, BAX, Caspase-3, and PCNA in xenograft tumor tissues." (PMID 34686673, 2021). "Different authors reported direct and indirect correlation between BCL2 protein and STATs or CRKL in different tumor models, supporting, thus, our data." (PMID 34884309, 2021). "Akt plays a central role in downstream cascade like the activation of proto-oncogenes, such as NF-κB, Wnt, MMP, BCL-2, and VEGF, as well as suppressing tumor-suppressor genes like FOXO1, Bax, Caspase, and Cycs." (PMID 34204873, 2021). "Because PFK15 attenuated proliferation and reduced Bcl-2/Bax ratio in both cancer and activated endothelial cells, we investigated the in vivo effects of PFK15 on tumor growth." (PMID 33922320, 2021). "By reducing the levels of Bcl2, Mcl1, CCND1, and WNT3A, miR-15a and miR-16 exert tumor suppressor functions." (PMID 33805590, 2021). "These drugs have also been shown to inhibit tumor progression by altering the expression levels of proteins related to cell cycle and apoptosis such as CCNE1, CDK4 and BCL-2, and by inhibiting drug efflux pumps." (PMID 35155562, 2021). "The most significant downregulated proteins identified were CD45, BCL-2 and CD20: likely reflecting changes in HCL tumour burden." (PMID 34561502, 2021). "Landmark studies in mice doubly transgenic for BCL-2 and MYC developed tumours much more rapidly than mice expressing either transgene alone." (PMID 33799592, 2021). "Using cutoff values of 40%, 50%, and 50% positive tumor cells for MYC, BCL-2, and BCL-6, respectively, 108 (55.4%) were positive for MYC, 129 (66.2%) cases were positive for BCL-2, and 115 (58.9%) cases were positive for BCL-6." (PMID 34804942, 2021). "In cancer cells, miR-1 works as a tumor suppressor and can target directly or indirectly a plethora of proteins, including MMP-2, MMP-9, and the antiapoptotic protein BCL2, which is considered one of the main targets of the tumor-suppressive action of miR-1." (PMID 34575852, 2021). "For example, some anti-apoptotic proteins such as Bcl-2 have been correlated with increased CCR7 expression in other tumor diseases and in non-tumor CD8+ T cells." (PMID 33841445, 2021). "The change of BCL2 and PIM1 indicated the role of SPATS2-mediated p-STAT3 in HCC tumor growth, limitless replicative potential and resistance to apoptosis." (PMID 33391405, 2021). "Among them, Mcl-1 and Bcl-2 exerted anti-apoptotic effects in HCC cells, c-Myc and VEGF showed strong pro-tumor growth effects, and TIMP-1 was involved in the regulation of HCC metastasis." (PMID 34408811, 2021).
tumor (continued). "Consistent with the previous finding that palmitoylation of GNA13 is required for its tumor suppressor function, ectopic expression of palmitoylation mutants of GNA13 were found to be incapable of suppressing the expression of BCL2 in SU-DHL4-shGNA13UTR cells." (PMID 33423045, 2021). "It activated tumour survival signalling and restored the induction of EMT, accompanied by decreased pro-apoptotic Bax and increased anti-apoptotic Bcl2." (PMID 34226501, 2021). "This treatment suppressed primary tumor growth and inhibited lung metastasis formation in 4T1 tumor-bearing mice as a result of matrix metalloproteinase-9 (MMP)-9 and Bcl-2 level downregulation as well as E-cadherin upregulation." (PMID 34884550, 2021). "On the contrary, plenty of in vitro studies have proved that IFO inhibits tumor growth by inducing cancer cell apoptosis such as the TUNEL and Bcl-2 expression elevation." (PMID 34631675, 2021). "Compared to bystander memory T cells, the tumor-specific TIL exhibited significantly higher expression levels of GzmB, PD-1, TIM-3, and significantly lower expression levels of Bcl-2, and significantly reduced proportions of CD62L+ cells." (PMID 34867942, 2021). "ROR1 expression was identified in 93% (52/56) of SCLC tumors, while BCL2 expression was identified in 86% (48/56) of SCLC tumors, and 83% (45/56) of SCLC tumors showed expression of both ROR1 and BCL2 in the same tumor cells." (PMID 34088900, 2021). "The regulators of apoptosis also include the anti-apoptotic protein Bcl-2 (B cell lymphoma/leukemia-2) and the pro-apoptotic protein BAX, which affect the function of cell caspases; in many neoplasms, an increase in Bcl-2 expression is often observed." (PMID 34830452, 2021). "Our study also determined the tumor-suppressing function of SNHG1 knockdown at molecular levels, corresponding to reductions in MMP-2, MMP-9, Bcl-2, and N-cadherin and elevations in Bax and E-cadherin." (PMID 34095464, 2021). "Early studies positively and negatively correlated response to venetoclax to Bcl-2 and Bcl-xL or Mcl-1 protein expression, respectively, and to mitochondrial priming by BH3 mimetic peptides ex vivo in tumor cells." (PMID 34885077, 2021). "In the immunohistochemical study, tumor cells showed positivity for CD34, CD99, and BCL2 and negativity for EMA, protein S100, and glial fibrillary acidic protein." (PMID 34211794, 2021). "In vitro regulation of PPP3CC expression through miR-200c-3p and RNA interference technology led to a concomitant modulation of BCL2- and p-AKT-related pathways, suggesting the tumor suppressive role of PPP3CC in EOC." (PMID 34573382, 2021). "The sensitivity of detecting Ta tumor was also superior to the reported methylation assays by DLX1 and ITGA4 (50.0–84.6%) and BCL2, CDKN2A and NID2 (61.1%)." (PMID 33902700, 2021). "The first BCL-2-selective BH3 mimetic to be tested and approved, venetoclax, can be dosed in patients to effectively inhibit BCL-2 and drive robust anti-tumor efficacy." (PMID 34065859, 2021). "Immunohistochemical analysis of the resected tumor revealed that the tumor cells expressed positive results for CD34, vimentin, and Bcl-2, focally positive for cytokeratin AE1/AE3, and weakly positive for STAT6." (PMID 33188464, 2020). "Some pan-Bcl-2 inhibitors were prepared, such as ABT-737, and can suppress tumor formation and survival." (PMID 32404045, 2020). "Although we discovered that CUEDC1 inhibited Bcl-2, C-myc, CyclinD1 and CDK4 expression and facilitated Bax expression, we did not fully elucidate the detailed mechanism by which CUEDC1 promotes tumor growth." (PMID 33099540, 2020). "The oral administration of KCP10043F decreased tumor growth in an A549 xenograft mouse model, as associated with the reduced phosphorylated STAT3, survivin, Mcl-1, and Bcl-2 expression and increased TUNEL staining and PARP cleavage in tumor tissues." (PMID 32150979, 2020).
tumor (continued). "An incisional biopsy of the oral mass was performed, the immunohistochemistry showed that the tumor cells tested positive for myeloperoxidase, CD4, BCL-2, KI-67." (PMID 33120806, 2020). "Heavy ion beams can exert anti-tumor effects by upregulating the pro-apoptotic gene BAX and inhibiting the anti-apoptotic gene BCL2, which inhibits MMP2 and MMP9 expression and angiogenesis in tumors." (PMID 33330321, 2020). "Tumor cells infected by Epstein–Barr virus (EBV) express latency proteins, among which LMP1 is able to increase the level of the anti‐apoptotic protein BCL‐2, today considered as an attractive target for therapeutic strategies." (PMID 32623836, 2020). "The data collected by the authors suggested that the best method for identifying all HGBL-DH/TH tumours is to perform FISH for the MYC rearrangement for all cases; when FISH testing is positive, BCL2 and BCL6 gene aberrations should be investigated." (PMID 31940809, 2020). "The Bcl-2 expression has been reported in more than half of patients with GBM and Bcl-2 overexpression significantly enhanced tumor resistance against cytotoxic agents." (PMID 32430842, 2020). "On immunostaining, the tumor is diffusely and strongly positive for CD34, an antigen in fibroblastic cells, as well as vimentin and Bcl-2." (PMID 31848901, 2020). "Tumor tissues were assessed by Western blotting, which revealed that the levels of Beclin1, LC3II/I, p-Bcl-2/Bcl-2, Bax, and caspase-3 were increased in sh-LETM1 tumor tissues compared with NC tumor tissues." (PMID 33552978, 2020). "Most tumor cells are strongly positive for vimentin; CD99 and Bcl-2 are also expressed in some cells." (PMID 32011484, 2020). "Knocking down HMGN5 decreased the expression of Bcl-2, Cyclin D1, MMP-2, and MMP-9 and increased the expression of Bax and p21 which is related to the malignant phenotype of tumor proliferation, migration, and invasion." (PMID 32596388, 2020). "Meanwhile, we studied the expression level of BCL-2 and BCL-XL of different treatment group by Westernblot assay of tumor tissue moved from DLBCL xenograft and turned out the similar result to cell lines." (PMID 32127939, 2020). "However, active effectors (BAX and BAK) or initiator (PMAIP1, BIK and BID) cannot lead to apoptosis in tumours, and these pro‐apoptotic proteins may be sequestered by guardians (BCL2 and BCL2L1) that have more potent enhancer activity to propel the anti‐apoptotic mechanisms." (PMID 32419250, 2020). "NuBCP-9, a Nur77-derived peptide, induces a conformational change, exposing the Bcl-2 BH3 domain, finally inhibiting tumor growth in vitro and in vivo." (PMID 32455818, 2020). "Fortunately, the significance of the expression of IHC biomarkers, such as the Bcl-2, bcl-6, and MYC proteins, in tumor cells has also attracted much attention." (PMID 32195944, 2020). "In one study, TSLP produced by myeloid cells after activation with tumor cell-derived IL-1α activated anti-apoptotic pathways in TSLPR-expressing tumor cells, through Bcl-2." (PMID 33042121, 2020). "The BCL2, IL1-β, GFAP and KI67 levels in C6 tumor cells exposed with Ator and MSCs significantly activated compared to control sample." (PMID 32981013, 2020). "Among them, BCL2 and CDK6 were found downregulated at mRNA levels and then confirmed at protein levels in primary patient-derived cancer cells and tumor lysates from mice upon BORA depletion." (PMID 32268485, 2020). "Another dual BCL-2 and BCL-XL inhibitor, AZD4320 shows potent tumor regression in vivo in hematological and solid malignancies." (PMID 32335811, 2020).
tumor (continued). "Marked overexpression of DUSP4, CD44, MUM1/IRF4, BCL-2, CD146/MUC18, IGF1R, and AKT3 was observed in the tumour cells in all mUM, compared to the background hepatocytes." (PMID 33008022, 2020). "The xenograft tumor had an expression of human CD20, CD19, CD79α, Ki67, Bcl-2, MUM-1 by immunohistochemistry." (PMID 31892981, 2020). "It has been suggested that ATRA can inhibit Bcl‐2 expression by activating RAR, thereby promoting tumour cell apoptosis." (PMID 33090723, 2020). "Total RNA was extracted from the tumor tissue, and the mRNA levels of Bax and Bcl-2 were evaluated by qPCR: in the BITC groups, higher expression of Bax and lower expression of Bcl-2 were observed." (PMID 33263014, 2020). "BCL2, the anti-apoptotic protein, was significantly decreased (8.2-fold) following TPT treatment in the breast MCF-7 tumor cells, suggesting an apoptosis-based cell death." (PMID 32765594, 2020). "Pro-metastatic neutrophils isolated from eIF4ES209A/S209A-bearing mice also manifest a decreased protein expression of anti-apoptotic factors BCL2 and MCL1, implicating the role of phospho-eIF4E in creating an anti-tumor microenvironment." (PMID 32517051, 2020). "Immunohistochemical staining revealed that the tumor cells were positive for STAT6, CD34, CD99, and BCL2." (PMID 32638177, 2020). "Among them, 6 genes including BCL2, BCL2L11, BAD, CASP7, CASP9, and CYCS expression reduced in tumor tissue compared to normal according to meta-analysis studies and RNA-seq TCGA data." (PMID 33292233, 2020). "ABT-737, the first BH3 mimetic inhibitor of BCL2, BCL-XL and BCL-W, exhibits favorable single-agent anti-tumorous activity in various tumor models." (PMID 33126914, 2020). "In growing tumours, the pro-apoptotic BH3-only protein PUMA is normally sequestered by BCL-2 and stabilised." (PMID 33066609, 2020). "In our cases, the immunohistochemistry showed that all the tumor cells were CK, CK7, EMA, Ber-EP4, and Bcl-2 positive." (PMID 31912868, 2020). "To compare EGFR, BCL-2, and BCL-XL expression levels within these tumor models, we performed IHC assays and H-score (H) assessment for each protein." (PMID 33256808, 2020). "The levels of cleaved caspase-3, -8, -9, and Bax increased with drug concentration, while Bcl-2 and Bcl-xL levels decreased, demonstrating that DCZ0858-activated tumor cell apoptosis in a dose-dependent manner." (PMID 32296013, 2020). "The combination of DT2216 (15 mg/kg, q7d, ip) and ABT-199 (50 mg/kg, qd, po) induced nearly complete suppression of tumor growth in mice xenografted with NCI-H146 SCLC cells, which depend on both BCL-XL and BCL-2 for survival." (PMID 34296214, 2020). "A contrasting study has shown that CXCL8 secreted by tumor cells activates proangiogenic and anti-apoptotic pathways by promoting the expression of VEGFA and bcl-2 at the invasion front, which confirms the key role of CXCL8 in tumor progression." (PMID 32201645, 2020). "Among the possible mechanism at the origin of BCL-2 overexpression, the E3 ubiquitin ligase, F-box only protein 10 (FBXO10), that targets BCL-2 for UPS-mediated degradation, is downregulated in MCL tumor cells." (PMID 32545704, 2020). "Using the PDX model, after treatment with gemcitabine, the Western blotting result showed that, tumor tissue with higher expression of FOXM1 presents higher p-P65 and Bcl2 levels and and low levels of Bax expression." (PMID 30782607, 2019). "effects on cancer cells and tumor growth through activation of such target genes as VEGF, MMP-2 and BCL2." (PMID 31772141, 2019). "To validate these in vitro result, we also measured expression level of BCL-2 and BAX protein expression in xenograft tumor." (PMID 31450709, 2019).